EGFR (epidermal growth factor receptor)
Diseases named in the same sentence as EGFR in open-access papers (continued):
Sharing a sentence is not in itself a finding about the gene and the disease.
astrocytoma (continued). "Higher distribution of EGFR Amp in our GBM patients was due to the addition of IDH-wildtype lower grade astrocytoma with amplified-EGFR into the GBM of the WHO CNS5 classification." (PMID 38595969, 2024). "Multiple factors are involved in the progression of astrocytoma; high expression of EGFR, cyclin D1, VEGF, and PR are features of this disease." (PMID 38553750, 2024). "Secondly, besides the gene mutation, the extrachromosomal DNA (such as EGFR amplification) and chromosome structure (such as chromosome 7 gain with 10 loss) are associated with higher AUP1 in IDH wildtype astrocytoma." (PMID 37029364, 2023). "EGFR was detected in 20.6% (7/34) of IDH1mt tumours including four astrocytomas (all grade 2) and three oligodendrogliomas (grade 2 n = 2, grade 3 n = 1)." (PMID 37568909, 2023). "EGFR is a valuable potential target for treating malignant astrocytomas because EGFR exerts activity at the top of a signaling cascade to mediate critical cellular functions." (PMID 36135196, 2022). "Limited by long-term survival data in our prospective cases, we performed retrospective review of the literature to explore further the prognostic significance of EGFR amplification within IDH-mutant astrocytomas." (PMID 35669011, 2022). "Although pharmacological treatments targeting EGFR or its downstream signaling pathway have been investigated, no significant benefit has been noted in unselected patients with high-grade astrocytomas." (PMID 36135196, 2022). "EGFR and integrin in astrocytoma frozen sections predict clinical outcome and correlate with radioresistance in vitro." (PMID 36212151, 2022). "Positive expressions of EGFR were observed mostly in the tumor cell membranes; in total, 54 (65.9%) of the 82 astrocytomas were positive for EGFR." (PMID 36135196, 2022). "Among the LGG data, the amplification frequencies of LANCL2 and EGFR in astrocytoma were the highest (7.33% and 13.92%, respectively), while those in oligoastrocytoma were the lowest (1.07% and 1.60%, respectively)." (PMID 34461927, 2021). "Of the 42 IDH-wild-type astrocytomas, 21 were classified as grade 4 using cIMPACT-NOW update 3 criteria and all had either TERTp mutation or EGFR amplification." (PMID 34257410, 2021). "By examination using MLPA KIT probemix P105, EGFR amplification was seen in 8 IDH-wild-type astrocytomas (19.0%), comprising 1 DA (5.6%) and 7 AAs (29.2%), tending to be slightly more frequent in AAs than in DAs (p = 0.109)." (PMID 34257410, 2021). "TERTp mutation and EGFR amplification have been reported as characteristics of IDH-wild-type GBM and as unfavourable prognostic factors in IDH-wild-type astrocytomas in many studies, although a few studies have reported no significance." (PMID 34257410, 2021). "Mutations in CHECK2, EGFR, PTEN, RYR2, and NF1 are instead associated with an IDH1-wildtype astrocytoma." (PMID 34503108, 2021).
astrocytoma (continued). "Diffuse astrocytomas, particularly wild-type (IDH-wt) astrocytomas, often present with EGFR and PTEN gene mutations, as well as chromosome 7 polysomy, loss of heterozygosity on chromosome 10q, and TERTp gene mutations." (PMID 33673851, 2021). "All DAs with EGFR amplification or + EGFR/-PTEN showed TERTp mutation, so all DAs diagnosed as “astrocytoma, grade 4” were equivalent to DAs with TERTp mutation, while 3 TERTp-wild type AAs showed EGFR amplification." (PMID 34257410, 2021). "FKBP1A has also been shown to inhibit TGF-beta type 1 receptor and it was found overexpressed in childhood astrocytomas, which presented as the EGFR/FKBP12/HIF-2alpha pathway." (PMID 32497068, 2020). "For astrocytoma, BRAF, ATM, CDKN2A, and EGFR mutations/amplifications were highly enriched in our cohort." (PMID 32373528, 2020). "Secreted phospholipase A2 group IIA (PLA2G2A) was shown to induce phosphorylation of the EGFR to induce proliferation through a PKC-dependent pathway in human astrocytoma in vitro." (PMID 30626092, 2019). "STAT3 activation is found to be higher in GBM than in low-grade astrocytoma, and it is co-expressed with EGFR in GBM." (PMID 31215502, 2019). "In consistency with our results, Guha and coworkers reported a characteristic gain-of-function for EGFR signaling pathway in Ras-B8 astrocytomas (12 V-Ha-Ras transgenic mouse model)." (PMID 25425962, 2014). "The potential effect of VRK2 was studied by analyzing the growth characteristics of astrocytoma cell lines with different EGFR/VRK2 protein ratios." (PMID 24079673, 2013). "Next, it was determined if the growth rate of these three astrocytoma cell lines was in accordance with their EGFR/VRK2 ratio." (PMID 24079673, 2013). "Similar to targeted therapies that tackle a gain-of-function in cancer, such as EGFR inhibitors, the introduction of the antagonist specific to oncomiRNA miR-335 interferes with the oncogenic properties of astrocytoma cells and induces therapeutic responses." (PMID 21592405, 2011). "Even though there are several studies advocating the importance of EGFR in the oncogenesis of astrocytomas, the prognostic role of EGFR overexpression and EGFR gene amplification is still not fully clarified." (PMID 20331873, 2010). "In the cohort of the IDH-wt astrocytomas the TERT promoter was mutated in 28 of 41 analyzed patients (68.3%); EGFR amplification was detected in 23 out of 48 analyzed patients (47.9%); and nuclear ATRX loss was detected in 12 (9.6%) patients, while it was retained in 113 (90.4%)." (PMID 41466163, 2025). "Similarly, recent studies have identified EGFR alteration as an additional adverse prognostic marker in IDH-mutant astrocytoma." (PMID 41460424, 2025). "Similarly, compared to astrocytomas and oligodendrogliomas, EGFR+ tumor cells also showed an upward trend in GBM (right)." (PMID 40264576, 2025). "Thus, a gain of chromosome 7 with amplification of the epidermal growth factor receptor (EGFR), deletion of chromosome 10, PTEN abrogation, CDKN2A/2B loss on chromosome 9 are noted in the peritumoral zone of gliablastomas and some astrocytomas." (PMID 39539752, 2024).
astrocytoma (continued). "The purpose of this study was to determine the safety, feasibility, and immunologic responses of treating grade 4 astrocytomas with multiple infusions of anti-CD3 x anti-EGFR bispecific antibody (EGFRBi) armed T cells (EGFR BATs) in combination with radiation and chemotherapy." (PMID 38263486, 2024). "The only exceptions are also the presence of CDKN2A/B homozygous deletion for IDHm astrocytoma, and of TERT promoter mutation, EGFR gene amplification, and chromosome 7 gain/chromosome 10 loss for IDH wild-type diffuse astrocytomas, which classify them as grade IV, which were missing in our study." (PMID 37534252, 2023). "Third, IDH wild-type astrocytomas with TERT promoter mutations, EGFR amplification, and + 7/− 10 chromosome copy number changes need to be further considered in future study to fully elucidate the intratumoral heterogeneity of IDH wild-type GBM according to the WHO CNS5." (PMID 37993907, 2023). "However, available surgery, radiation therapy, and experimental therapies such as adjuvant therapy, anti‐angiogenic therapy, and EGFR‐targeting antibody drug are the usual treatment for most types of astrocytoma." (PMID 37675821, 2023). "Additionally, in another rare case report, a spinal cord gemistocytic astrocytoma was immunonegative for EGFR." (PMID 37835664, 2023). "Thus, in these ‘discrepant’ cases, tumor cells harbored a relatively low degree of amplification relative to classic cases of EGFR-amplified IDH-wildtype astrocytoma that often harbor 10's to 100's of copies of the gene, often episomally." (PMID 36397144, 2022). "Alterations in EGFR expression are also observed in astrocytomas and may affect gliogenesis by promoting proliferation and modifying angiogenesis and invasion." (PMID 35454784, 2022). "The presence of both EGFR amplification and IDH mutation in these high-grade astrocytoma tumors was unusual and raised questions within our clinical team in regards to the tumors’ correct nomenclature, biological behavior, possible syndromic genomic instability, and, ultimately, patient prognosis." (PMID 35669011, 2022). "Given that FKBP1A is a component of the EGFR/FKBP1A/HIF-2α pathway, which plays a role in childhood high-grade astrocytomas, increased FKBP1B levels may also cause astrocytomas." (PMID 28394947, 2017). "EGFR aberrations including gene amplification and EGFRvIII mutation, PTEN mutation, as well as TOP2A, RRM1 and TS overexpression were significantly more prevalent in GBM than grade III astrocytomas." (PMID 26933808, 2016).
astrocytoma (continued). "In vitro studies indicate that progesterone promotes cell proliferation in astrocytomas, as well as the expression of genes that are important for tumor growth and dissemination, e.g., cyclin D1, epidermal growth factor receptor (EGFR) and vascular endothelial growth factor (VEGF) 35,36." (PMID 27626480, 2016). "Notably, there is a precedent for SULF modulation of EGFR signaling in that SULF2 knockdown in astrocytoma cells led to a reduction in EGFR activation, as well as that of several other receptor tyrosine kinases." (PMID 23950901, 2013). "The same authors also demonstrated that progesterone increased VEGF and EGFR expression, and cell proliferation in two human astrocytoma cell lines derived from tumors of different evolution grades (U373 grade III and D54 grade IV) and these effects were inhibited by Mifepristone." (PMID 23530939, 2013). "An amplified EGFR gene may lead to expression of mutant EGFR (EGFRvIII) in high grade astrocytomas, providing a possible target for immunotherapy." (PMID 20331873, 2010). "We also identified several mutations not previously reported in pediatric astrocytoma, some of which (EGFR, PIK3CA, PDGFRA) represent potentially actionable targets." (PMID 19924296, 2009). "Interaction of the EGFR and versican has been demonstrated for transfected astrocytoma U87 cells." (PMID 17662123, 2007). "ATRX loss was indicative of non-amplified EGFR, largely in astrocytoma." (PMID 37665980, 2023). "For example, research suggests that grade II or III IDH wild-type astrocytomas may harbor chromosomal +7/-10, epidermal growth factor receptor (EGFR) amplification, and/or telomerase reverse transcriptase promoter (TERT) alterations, with the same prognosis as GBMs." (PMID 35965542, 2022). "We considered the possibility that excessive genomic instability may have led to EGFR amplification in our cases and therefore also tested the four cases on a classifier that includes primary mismatch repair-deficient IDH-mutant astrocytomas (PMMRDIA) as a separate category." (PMID 35669011, 2022). "For TERTp mutation, EGFR highcopy amplification and CDKN2A homozygous deletion (recommended as upcoming diagnostic markers in the cIMPACT now update 3 and in a novel grading system for IDH-mutant astrocytomas) clinical sensitivity and specificity was equally 100%." (PMID 32758285, 2020). "In high-grade astrocytomas such a discrepancy may be due to EGFR gene mutation and truncated receptors, which have not been reported in meningiomas." (PMID 28367377, 2017). "Additionally, the most frequent molecular abnormalities presented in astrocytomas (LOH 10p and LOH 10q; TP 53 mutations; EGFR amplification/chromosome 7 polysomy; EGFRvIII variant; CDKN2A deletions; IDH1 mutations) were used as markers of neoplastic cells at the DNA level." (PMID 25788865, 2014). "The same authors also demonstrated that progesterone increased VEGF and EGFR expression and cell proliferation, Mifepristone was able to inhibit not only the progesterone effects but also when it was administered alone significantly reduce astrocytoma cell growth in vitro." (PMID 23530939, 2013). "By contrast, IDH1/2-mutant astrocytomas had a broader range of cooccurring deleterious alterations across various pathways, including between CDKN2A/B and EGFR." (PMID 39164213, 2025). "EGFR Amp was more common in IDH-wildtype diffuse gliomas (66.0%) and GBM (85.5%) than IDH-mutant diffuse gliomas (32.2%) and its subtypes (astrocytoma, 29.3%; oligodendroglioma, 34.8%)." (PMID 38595969, 2024).
astrocytoma (continued). "In grade 2–3 astrocytoma, variations in FGFR4, KIT, NTRK2, and positive immunohistochemistry for ATRX and EGFR showed statistically significant results in univariate survival analysis." (PMID 38970209, 2024). "For example, EGFR amplification rates in grade II, III, and IV astrocytomas are 0–4%, 0–33%, and 34–64% respectively." (PMID 39063215, 2024). "Several previous studies included IDH-mutant GBM which is defined as IDH-mutant astrocytoma (WHO grade 4) currently, and examined EGFR Amp, with the ratio ranging from 3% to 16%." (PMID 38595969, 2024). "This phase I study used a 3 + 3 dose escalation design to test the safety and feasibility of intravenously infused EGFR BATs in combination with radiation and temozolomide (TMZ) in patients with newly diagnosed grade 4 astrocytomas (AG4)." (PMID 38263486, 2024). "The MAPK cascade, the leader of Ras‐Raf‐ERK signaling pathways, is a common signaling mechanism in astrocytoma, leading to activation of PDGFR, EGFR, AKT, PTEN, and PTEN." (PMID 37675821, 2023). "However, the outcome of IDH-wt astrocytomas is strictly related to several genetic features such as K27M mutation of histone 3 family 3A (H3F3A; H3-K27M); V600E mutation of B-rapidly accelerated fibrosarcoma (BRAF); pTERT-mut; EGFR-amp; and chromosome 7 gain, and chromosome 10 loss." (PMID 35756624, 2022). "The 4 discrepant cases were IDH-wildtype infiltrating astrocytomas which by FISH all had average EGFR signals per nucleus > 4 (range 4.48–6.62) and ratio of EGFR signals/CEP7 signals (a centromeric probe) > 2 (range 2.1 -2.92)." (PMID 36397144, 2022). "Patients affected by high grade astrocytoma displayed alterations involving PIK3CA (40%), EGFR (40%) and RAS (20%) as previously reported." (PMID 35372034, 2022). "Amphiregulin (AREG), one of the ligands of epidermal growth factor receptor (EGFR) 3, has been observed in malignant astrocytoma 4–6 and is responsible for activating complex pathway networks, including Ras/MAPK, PI3K/Akt, PLC γ, and stat." (PMID 36160033, 2022). "Interestingly, no astrocytomas with + EGFR/− PTEN lacked the TERTp mutation." (PMID 34257410, 2021). "Epidermal growth factor receptor (EGFR) is a tyrosine kinase, which is commonly activated or overexpressed in malignant astrocytoma, with the most common form of recombinant amplification being the EGFR variant type III (EGFRvIII)." (PMID 32922947, 2020). "Pediatric low grade astrocytoma and ependymoma cell lines showed high percentages of cells expressing VEGFR-1, FGFR-1, EGFR, HGFR and RON (respectively 52–77%, 34–51%, 63–90%, 83–98%, 65–95%, compared to isotype controls)." (PMID 25799134, 2015). "Several of these genes, including MYC, EGFR, HIF1A, HGF, APOE, TIMP3, and WNT5A have been identified as being important to development of astrocytoma." (PMID 23737970, 2013). "EGFR amplification was identified in 23 of 61 GBMs (37.7%) and in one of the seven WHO grade III astrocytomas (14.3%)." (PMID 24083241, 2013). "In non-TCGA IDH1/2-mutant astrocytomas, CCND2 alteration (HR: 3.05), EGFR amplification (HR: 2.43), CDKN2A/B loss (homozygous or heterozygous loss, HR: 2.28), 22q loss (HR: 1.97), and PDGFRA alteration (HR: 1.92) were negatively prognostic." (PMID 39164213, 2025). "V12Ha-Ras transgenic mice under the control of the GFAP promoter form astrocytomas that have the added genetic complexity of the aberrant expression of p16, p19, and PTEN while overexpressing EGFR, MDM2, and CDK4, with chromosomal rearrangements comparable to human astrocytomas." (PMID 41154198, 2025). "A recent study suggested that EGFR Amp in WHO grade 4 IDH-mutant astrocytoma was not related to worse OS, unless CDKN2A/B homozygous deletion were also detected." (PMID 38595969, 2024).